KPNA2 (karyopherin subunit alpha 2)
Description:
Functions in nuclear protein import as an adapter protein for nuclear receptor KPNB1. Binds specifically and directly to substrates containing either a simple or bipartite NLS motif. Docking of the importin/substrate complex to the nuclear pore complex (NPC) is mediated by KPNB1 through binding to nucleoporin FxFG repeats and the complex is subsequently translocated through the pore by an energy requiring, Ran-dependent mechanism. At the nucleoplasmic side of the NPC, Ran binds to importin-beta and the three components separate and importin-alpha and -beta are re-exported from the nucleus to the cytoplasm where GTP hydrolysis releases Ran from importin. The directionality of nuclear import is thought to be conferred by an asymmetric distribution of the GTP- and GDP-bound forms of Ran between the cytoplasm and nucleus. Mediator of PR-DUB complex component BAP1 nuclear import; acts redundantly with KPNA1 and Transportin-1/TNPO1.
Synonyms: RCH1; SRP1alpha; IPOA1; QIP2; PTAC58; SRP1-alpha
Tractability: PROTAC: UniProt records ubiquitination sites on it; ubiquitination databases record sites on it; its protein half-life has been measured; a small molecule that binds it is known.
Gene: Protein-coding gene on chromosome 17 (68,035,636 to 68,047,364, forward strand). Ensembl gene ENSG00000182481.
Subcellular location: Cytoplasm; Nucleus; Endoplasmic reticulum membrane; Golgi apparatus membrane
Subcellular location (Human Protein Atlas): Nucleoplasm; Cytosol
Pathways (Reactome):
Disease: Maturation of DENV proteins; NS1 Mediated Effects on Host Pathways; SARS-CoV-1 activates/modulates innate immune responses; SARS-CoV-2 activates/modulates innate and adaptive immune responses
Signal Transduction: CaMK IV-mediated phosphorylation of CREB; Estrogen-dependent gene expression
DNA Repair: Sensing of DNA Double Strand Breaks
Immune System: ISG15 antiviral mechanism
Neuronal System: CREB1 phosphorylation through the activation of CaMKII/CaMKK/CaMKIV cascasde
Gene Ontology:
Molecular function: histone deacetylase binding; nuclear import signal receptor activity; protein binding; RNA binding
Biological process: entry of viral genome into host nucleus through nuclear pore complex via importin; NLS-bearing protein import into nucleus; positive regulation of type I interferon production; positive regulation of viral life cycle; protein import into nucleus; DNA metabolic process; regulation of DNA recombination
Cellular component: cytoplasm; cytosol; Golgi membrane; membrane; NLS-dependent protein nuclear import complex; nuclear membrane; nucleoplasm; nucleus; endoplasmic reticulum membrane; host cell
Genetic constraint (gnomAD): Loss-of-function variants: 19 observed, 39.53 expected, observed/expected ratio (o/e) 0.48, 90% interval 0.33 to 0.7. The upper end of that interval is the gene's LOEUF score, 0.7, which puts it in group 2 of 6, group 1 being the genes least tolerant of losing a copy. Missense variants: 440 observed, 557.68 expected, observed/expected ratio (o/e) 0.79, 90% interval 0.73 to 0.85. Synonymous variants: 197 observed, 201.73 expected, observed/expected ratio (o/e) 0.98, 90% interval 0.87 to 1.1.
Homologues: Orthologues: chimpanzee KPNA2 (99% identical), macaque KPNA2 (99% identical), rat Kpna2 (95% identical), mouse Kpna2 (95% identical), mouse Kpna2rt (95% identical), rat Kpna2l1 (93% identical), tropical clawed frog kpna2 (77% identical), zebrafish kpna2 (74% identical), Caenorhabditis elegans F53B2.5 (22% identical), Caenorhabditis elegans ima-1 (21% identical). Paralogues in human: KPNA7 (53% identical), KPNA4 (51% identical), KPNA3 (50% identical), KPNA5 (48% identical), KPNA1 (47% identical), KPNA6 (47% identical).
Diseases named in the same sentence as KPNA2 in open-access papers:
KPNA2 is named in the same sentence as 124 diseases in open-access papers, as found by Europe PMC text mining. Sharing a sentence is not in itself a finding about the gene and the disease. The quoted sentences say what the papers report.
breast carcinoma (52 papers, 2008 to 2025). "Aberrant expression of KPNA2 is closely associated with the occurrence and progression of various cancers, especially gallbladder cancer, colorectal cancer and breast cancer, where its pro‐tumorigenic properties have been widely confirmed." (PMID 40830912, 2025). "KPNA2, which encodes for Karyopherin-α2 is also highly expressed in breast cancer and its expression is associated with aggressiveness, poor outcomes in addition to chemotherapy and radiotherapy resistance." (PMID 33662042, 2021). "Therein, miR-145, miR-204 and miR-144 exhibited a significantly decreased level in cancer cases, and survival analysis suggested that the target gene KPNA2 of miR-144 was tightly associated with prognosis of patients with breast cancer." (PMID 32355466, 2020). "The purpose of this study was to explore the regulatory mechanism of the long non-coding RNA (lncRNA) LINC00461 underlying the breast cancer invasion and migration via the miR-144-3p/KPNA2 axis." (PMID 32355466, 2020). "KPNA2 is upregulated in multiple kinds of malignancies and high KPNA2 level is associated with adverse outcome of patients with breast cancer, colorectal cancer (CRC), and urothelial carcinoma and so forth." (PMID 31046781, 2019). "In breast cancer, KPNA2 overexpression was associated with poor outcome, but lack of statistical significance." (PMID 27974678, 2017). "Upregulation of KPNA2 expression has been implicated in several human cancers, including prostate cancer, esophageal squamous cell carcinoma, lung cancer, breast cancer, and infiltrative astrocytomas." (PMID 24070213, 2013). "KPNA2 has been proposed to be a prognostic marker in breast cancer, and overexpression of this gene has been associated with poor prognosis, expression signatures of high proliferation, and tumor grade." (PMID 23382830, 2013). "One study showed KPNA2 to promote invasive phenotypes of human breast cancer cells in vitro, but the mechanism underlying this observation was not investigated." (PMID 23536776, 2013). "Our study is the first to associate KPNA2 expression with human OMGCTs development, other than human breast cancer as cited above." (PMID 22962582, 2012). "A series of reports suggest that KPNA2 expression is linked to breast carcinogenesis and acts as a potential prognostic marker for breast carcinomas." (PMID 22962582, 2012). "A series of recent reports have implicated KPNA2 expression's link to human tumorigenesis such as breast cancer." (PMID 22962582, 2012). "In many studies, KPNA2 has been linked to tumorigenesis (such as non-small cell lung cancer, breast cancers, and epithelial ovarian cancer), and the gene is highly expressed in many cancerous tissues, which is consistent with the expression of the APOBEC3B gene in this study." (PMID 35918642, 2022). "Meanwhile, it has been suggest that elevated KPNA2 could be associated with poor prognosis in a variety of solid tumors, including colorectal cancer, breast cancer, gastric cancer and hepatocellular carcinoma." (PMID 27974678, 2017). "Recently, a publication provided a novel sight for breast cancer treatment that KPNA2 and IL-6 associated inflammation could facilitate c-Myc nuclear translocation and regulate breast cancer development, and this similar mechanism has also been verified in our prostatic cancer cells." (PMID 34657603, 2021). "Mechanistic studies demonstrated that RBM15 stabilizes KPNA2 mRNA via m6A modification, thereby promoting breast cancer progression." (PMID 41403702, 2025). "Our study revealed strong positive correlations between KPNA2 and FOXM1, CCNB1, and CCNB2 expression, with a significant association with the G2/M checkpoint pathway in breast cancer patients." (PMID 40002266, 2025). "KPNA2 plays a crucial role in estrogen receptor alpha (ERα) signaling and breast cancer progression." (PMID 40002266, 2025).
breast carcinoma (continued). "Studies have demonstrated that KPNA2 expression shows a significant positive correlation with HER2 status in breast cancer, with notably higher expression levels observed in HER2-positive tumors compared to HER2-negative cases." (PMID 40002266, 2025). "The FOXM1 directly binds to and regulates CCNB1/CCNB2 promoters for breast cancer cell cycle progression, while KPNA2 modulates this process through its effects on FOXM1 nuclear transport and retention." (PMID 40002266, 2025). "Our study investigated the prognostic significance of FOXM1 expression specifically in HR+HER2- breast cancer patients with high KPNA2 levels." (PMID 40002266, 2025). "Studies have shown that KPNA2 is frequently overexpressed in breast cancer tissues compared to normal breast tissue and correlates with poor prognosis." (PMID 40002266, 2025). "The novel Ras membrane-bound regulator of Ras, Rce1, suggests a promising strategy for targeting Ras in breast cancer, and KPNA2 overexpression significantly enhances the invasion and migration capabilities of breast cancer cells." (PMID 39720180, 2024). "The association of the six top-ranked karyopherins (KPNA2, XPOT, CSEL1, KPNA1, KPNA4, and TNPO1) in the breast cancer datasets from Oncomine was analyzed using a Kaplan-Meier Plotter." (PMID 37928256, 2023). "We found that the expression levels of RACGAP1 and KPNA2 in breast cancer cells were positively relevant to cell cycle and proliferation through CancerSEA database." (PMID 36200070, 2022). "For example, USP1 increases the expression of pro-metastatic genes, especially nuclear protein KPNA2, and USP1 deubiquitinates KPAN2 by interacting with KPAN2, thereby promoting the metastasis of breast cancer via stabilization of KPNA2." (PMID 36153316, 2022). "Especially, KPNA2 has been reported to be associated with cancer cell motility and patient survival in breast cancer and non-small-cell lung cancer; therefore, we focused on KPNA2 for the further studies." (PMID 35884546, 2022). "Studies have revealed that KPNA2 is abnormally expressed and as a poor prognosis predictor for multiple malignancies, including hepatocellular, bladder and breast carcinoma, and malignant melanoma." (PMID 34034774, 2021). "Recently, higher expression of KPNA2 was demonstrated in breast cancer, burkitt lymphoma, melanoma, bladder cancer, and correlated with the poor prognosis of patients." (PMID 34034774, 2021). "For instance, KPNA2 has been demonstrated to harbor the oncogenic property of promoting malignant phenotypes of breast cancer cells." (PMID 33731128, 2021). "To make the findings more convincible, we used qRT-PCR to detect the expression levels of LINC00461 and miR-144-3p in breast cancer cells, and conducted western blot to determine KPNA2 protein level." (PMID 32355466, 2020). "In our study, LINC00461 was discovered to be considerably elevated in breast cancer via bioinformatics analysis, and survival analysis revealed that there was an intimate correlation between KPNA2 and prognosis." (PMID 32355466, 2020). "LINC00461 promoted the expression of KPNA2 by competitively binding to miR-144-3p, thereby promoting the invasion and migration of breast cancer cells." (PMID 32355466, 2020). "Bioinformatics analysis suggested that LINC00461 probably inhibited miR-144 to promote KPNA2 expression, consequently mediating cell invasion and migration in breast cancer." (PMID 32355466, 2020). "Our study described that KPNA2 was highly expressed in breast cancer and was identified to be a direct target of miR-144-3p by applying RIP and dual-luciferase reporter assay." (PMID 32355466, 2020). "More recently, USP1 has been found to deubiquitinate and stabilize KPNA2, leading to pro-metastatic functions in breast cancer." (PMID 33114077, 2020).
breast carcinoma (continued). "Previous studies have demonstrated that KPNA2 is a potential biomarker in multiple forms of cancer, including breast cancer, lung cancer, gastric cancer, colon cancer, prostate cancer and upper tract urothelial carcinoma." (PMID 33176814, 2020). "LINC00461, KPNA2 and miR-144-3p were identified, and KPNA2 was predicted to be a target of miR-144-3p and significantly correlated with breast cancer prognosis." (PMID 32355466, 2020). "Many studies have reported that KPNA2 is highly expressed in diverse types of cancer, including breast cancer, gastric cancer, hepatocarcinoma, lung cancer, melanoma, and ovarian cancer." (PMID 31212646, 2019). "In the breast cancer core network, we found Fibronectin 1 (FN1), which is related to migration; FLT4 involved in angiogenesis; GSK3B, an anti-proliferative enzyme; KPNA2, a nucleopore transporter and the EP300-associated transcriptional activator NCOA3." (PMID 28775339, 2017). "Aberrant, high KPNA2 expression has been observed in many cancer types, including breast cancer, melanoma, cervical cancer, esophageal cancer, lung cancer, ovarian cancer, prostate cancer, bladder cancer, brain cancer and liver cancer." (PMID 28422734, 2017). "Abnormal expression level of KPNA2 has been reported in numerous malignancies tumors, such as gastric adenocarcinoma, breast cancer and lung cancer." (PMID 27611951, 2016). "In recent years, KPNA2 has emerged as a potential biomarker in multiple forms of cancer, including breast carcinoma, lung cancer, melanoma, hepatocellular carcinima, and gastric carcinoma." (PMID 26626145, 2015). "The expression of CHD1, GREB1 or KPNA2 was required for estrogen-stimulated breast cancer cell growth." (PMID 24735615, 2014). "The results showed that the average expression levels of CHD1 and KPNA2 were significantly higher in breast cancers (P < 0.05) than in normal breast tissues." (PMID 24735615, 2014). "We further evaluated the expression levels of CHD1, GREB1 and KPNA2 mRNA in these breast cancer specimens by qRT-PCR." (PMID 24735615, 2014). "Depletion of either CHD1, GREB1 or KPNA2 significantly abrogated the enhanced growth of ER+ breast cancer cells due to miR-26 depletion." (PMID 24735615, 2014). "GREB1, CHD1 and KPNA2 were identified as novel targets of miR-26a/b and were demonstrated to be necessary for estrogen-promoted ER+ breast cancer cell proliferation." (PMID 24735615, 2014). "This study gives clear evidence that KPNA2 acts as a novel oncogenic factor in human breast cancer, in vitro." (PMID 22962582, 2012). "New research showed that forced KPNA2 expression drives malignant features relevant to breast cancer progression, while its silencing is required for the remission of those progressive phenotypes." (PMID 22962582, 2012). "Several studies indicated that KPNA2 extensive expression in breast cancer patients was associated with a short overall patient survival and recurrence-free survival, and may warrant consideration as a potential marker for chemoresistance in advanced breast cancer." (PMID 22962582, 2012). "However, the follow-up duration in our series is short, limiting our ability to demonstrate that HR+/HER2- breast cancer patients with high KPNA2 but low FOXM1 mRNA levels exhibit significantly better survival outcomes beyond the TCGA cohorts." (PMID 40002266, 2025). "Some new substrates of USP1 have also been found in several tumors, such as karyopherin subunit alpha 2 and ERa in breast cancer, ID2 in gastric cancer, c-kit and TBLR1 in liver cancer, TAZ in osteosarcoma and hepatocellular carcinoma, Snail in ovarian cancer, and PARP1 in cholangiocarcinoma." (PMID 39513905, 2024). "The results implied that RACGAP1 and KPNA2 might be a promising target in breast cancer therapy in the future." (PMID 36200070, 2022). "USP1 enhances breast cancer metastasis by deubiquitinating and stabilizing KPNA2." (PMID 34575114, 2021).
breast carcinoma (continued). "In addition, as expected, USP1 expression positively correlates with KPNA2 in breast cancer tissues." (PMID 34575114, 2021). "In addition, KPNA2 contributes to the poor prognosis of breast cancer by aberrant subcellular localization of DNA damage response proteins with subsequent impaired function." (PMID 34903711, 2021). "Also, the significance of KPNA2 as a nucleocytoplasmic transport protein in breast cancer has been recognized by virtue of its mediation of the subcellular localization of proteins associated with DNA damage response in breast cancer." (PMID 33731128, 2021). "There is evidence to indicate that KPNA2 is upregulated in breast cancer." (PMID 33962648, 2021). "Besides, LINC00461 and KPNA2 were found to be remarkably highly-expressed in breast cancer cells, while miR-144-3p was poorly-expressed." (PMID 32355466, 2020). "Therefore, we reasoned that LINC00461 regulated cell migration and invasion in breast cancer probably via inhibiting miR-144 to promote KPNA2 expression." (PMID 32355466, 2020). "Hence, the regulatory axis LINC00461/miR-144-3p/KPNA2 can be used as a promising therapeutic target in breast cancer treatment." (PMID 32355466, 2020). "Hence, to achieve a better understanding of the regulatory mechanism of the LINC00461/miR-144-3p/KPNA2 axis underlying cell invasion and migration in breast cancer, we divided cells into si-NC + oe-NC, si-LINC00461 + oe-NC and si-LINC00461 + oe-KPNA2 groups." (PMID 32355466, 2020). "Taken together, these results elucidated that silencing LINC00461 could inhibitory function on cell invasion and migration in breast cancer, and such effect could be reversed when KPNA2 was overexpressed." (PMID 32355466, 2020). "In breast cancer, KPNA2 knockdown could suppress the inflammatory responses and malignant progression of the tumor cells induced by IL-6." (PMID 33193737, 2020). "Since USP1 has been shown to regulate other targets, such as: KPNA2, that drive breast cancer metastasis, targeting this enzyme may be beneficial in the treatment of breast cancer patients, more specifically, TNBCs." (PMID 33114077, 2020). "Moreover, we determined that CHD1 and KPNA2 were necessary for estrogen-stimulated proliferation of breast cancer cells." (PMID 24735615, 2014). "We have therefore identified a novel estrogen/MYC/miR-26 axis that mediated estrogen stimulated cell growth via CHD1, GREB1 and KPNA2 and suggest that upregulation of miR-26a and miR-26b may be considered as novel strategy for breast cancer therapy." (PMID 24735615, 2014). "Furthermore, RBM15 may promote malignant progression and immune escape in breast cancer cells by regulating the stability of karyopherin subunit alpha 2 (KPNA2) mRNA5." (PMID 40370450, 2025). "Karyopherin alpha 2 (KPNA2), a nuclear transport protein, plays a crucial role in nucleocytoplasmic communication and the transport of tumor-related proteins, with its elevated expression strongly correlating with poor prognosis in breast cancer, particularly in aggressive subtypes." (PMID 40002266, 2025). "Additionally, their expression was positively correlated with that of Ki-67, PCNA and MCM2, which was consistent with the predictions of CancerSEA, implying that RACGAP1 and KPNA2 could facilitate breast cancer progression." (PMID 36200070, 2022). "Thus, it could be concluded that silencing LINC00461 played an inhibitory role in cell invasion and migration in breast cancer via targeting miR-144-3p to suppressing KPNA2." (PMID 32355466, 2020). "Besides, LINC00461 could mediate cell invasion and migration in breast cancer via the miR-144-3p/KPNA2 axis." (PMID 32355466, 2020). "Therefore, we further investigated whether KPNA2 silencing induces apoptosis of breast cancer MDA-MB-231 cells upon radiation and disturbs the nuclear transport of BRCA1 molecules." (PMID 31212646, 2019). "Forced expression of KPNA2 could increase proliferation of breast cancer cells." (PMID 27974678, 2017).